MEDAG (mesenteric estrogen dependent adipogenesis)
Description:
Involved in processes that promote adipocyte differentiation, lipid accumulation, and glucose uptake in mature adipocytes.
Synonyms: hAWMS3; MEDA-4; AWMS3; C13orf33; MEDA4; FLJ14834
Tractability: No criterion of Open Targets' tractability assessment is met for any kind of drug.
Gene: Protein-coding gene on chromosome 13 (30,906,271 to 30,925,572, forward strand). Ensembl gene ENSG00000102802.
Subcellular location: Cytoplasm
Gene Ontology:
Molecular function: protein binding
Biological process: positive regulation of fat cell differentiation
Cellular component: cytoplasm
Genetic constraint (gnomAD): Loss-of-function variants: 21 observed, 19.91 expected, observed/expected ratio (o/e) 1.05, 90% interval 0.75 to 1.52. The upper end of that interval is the gene's LOEUF score, 1.52, which puts it in group 6 of 6, group 1 being the genes least tolerant of losing a copy. Missense variants: 310 observed, 277.09 expected, observed/expected ratio (o/e) 1.12, 90% interval 1.02 to 1.23. Synonymous variants: 120 observed, 104.54 expected, observed/expected ratio (o/e) 1.15, 90% interval 0.99 to 1.34.
Homologues: Orthologues: chimpanzee MEDAG (99% identical), macaque MEDAG (98% identical), dog MEDAG (93% identical), pig MEDAG (92% identical), mouse Medag (91% identical), rat Medag (91% identical), rabbit MEDAG (89% identical), guinea pig MEDAG (81% identical), tropical clawed frog medag (39% identical).
Diseases named in the same sentence as MEDAG in open-access papers:
MEDAG is named in the same sentence as 15 diseases in open-access papers, as found by Europe PMC text mining. Sharing a sentence is not in itself a finding about the gene and the disease. The quoted sentences say what the papers report.
breast carcinoma (3 papers, 2021 to 2024). "Our study reveals that MEDAG is highly expressed in breast cancer and is associated with poor survival." (PMID 33462219, 2021). "MEDAG has been shown to regulate breast cancer (BC) progression and EMT via the AKT/AMPK/mTOR pathway, reducing chemosensitivity in BC cells." (PMID 38717641, 2024). "Regarding treatment, our study showed that MEDAG reduced epirubicin sensitivity in breast cancer cells and protected epirubicin-induced apoptosis through the AKT/AMPK pathway." (PMID 33462219, 2021). "In conclusion, we show the role and corresponding mechanism of MEDAG in breast cancer for the first time." (PMID 33462219, 2021). "Here, we demonstrate for the first time that MEDAG plays a role in breast cancer and extensively investigated the effects of MEDAG in vitro and in vivo." (PMID 33462219, 2021). "To further demonstrate the role of MEDAG in breast cancer, we used siRNA to knockdown MEDAG and a plasmid to overexpress this gene in MCF-7 and MDA-MB-468 cells." (PMID 33462219, 2021). "Invasion and migration assays were also performed and showed that MEDAG overexpression enhanced the pro-metastatic phenotype in the breast cancer cell lines." (PMID 33462219, 2021). "To investigate the underlying mechanism of MEDAG in the regulation of the progression and EMT of breast cancer, we performed a KEGG analysis of the DEGs according to the MEDAG levels in breast cancer." (PMID 33462219, 2021). "Given the in vitro results, we then established in vivo xenograft models to verify the role of MEDAG in breast cancer growth and metastasis." (PMID 33462219, 2021). "The in vitro results verified that the knockdown of MEDAG inhibited proliferation, the pro-metastatic phenotype and EMT in breast cancer, and that the overexpression of MEDAG had the opposite effect." (PMID 33462219, 2021). "In this study, we identified the role of MEDAG in breast cancer and determined the possible signaling pathway involved." (PMID 33462219, 2021). "Our results showed that MEDAG was highly expressed in breast cancer and that breast cancer patients with high MEDAG showed aggressive vascular invasion, lymph node metastasis, and poor disease-free survival." (PMID 33462219, 2021). "Taken together, our study examined the potential role and mechanism of MEDAG in breast cancer progression and chemosensitivity." (PMID 33462219, 2021). "To verify the clinical relevance of MEDAG in breast cancer, we examined MEDAG expression in 101 breast cancer tissues and 10 normal breast tissues." (PMID 33462219, 2021). "Furthermore, we reveal the functions of MEDAG in breast cancer progression and EMT by conducting cell-based studies and analyses of mouse models and human breast cancer samples." (PMID 33462219, 2021). "In contrast, MEDAG overexpression significantly reduced epirubicin sensitivity in breast cancer." (PMID 33462219, 2021). "Furthermore, the AKT inhibition blocked the effects of MEDAG overexpression on breast cancer progression and EMT." (PMID 33462219, 2021). "In addition, CCK-8 assays, Transwell assays with Matrigel, and wound-healing assays were performed to confirm the function of MEDAG in breast cancer." (PMID 33462219, 2021). "Therefore, our results show that MEDAG plays a crucial role in triggering EMT in breast cancer." (PMID 33462219, 2021). "However, knowledge regarding the function of MEDAG in breast cancer is limited." (PMID 33462219, 2021). "Moreover, we determined the mRNA level of MEDAG in 10 paired breast cancer and normal tissues." (PMID 33462219, 2021). "Moreover, increased chemosensitivity was observed in the MEDAG-silenced cancer cells, and MEDAG may modify the sensitivity of breast cancer cells to epirubicin by regulating the AKT/AMPK pathway." (PMID 33462219, 2021). "MEDAG promotes breast cancer cell proliferation, pro-metastasis, and EMT through the AKT/AMPK/mTOR pathway and reduces epirubicin sensitivity in breast cancer cells via AKT/AMPK." (PMID 33462219, 2021).
breast carcinoma (continued). "The results demonstrated that the breast cancer patients negative for MEDAG had a better disease-free survival (DFS) than the patients positive for MEDAG (P = 0.021)." (PMID 33462219, 2021).
type 2 diabetes mellitus (3 papers, 2021 to 2022). A type of diabetes mellitus that is characterized by insulin resistance or desensitization and increased blood glucose levels. "MEDAG is a novel adipogenesis gene involved in visceral obesity that is strongly associated with the onset and progression of type 2 diabetes and can increase the risk of obesity, which is related to the development and rupture of AAA." (PMID 35874515, 2022). "A recent study demonstrated that the MEDAG expression level was positively correlated with the hemoglobin A1c level and that MEDAG was overexpressed in the pancreatic islet tissue of type 2 diabetes mellitus (T2DM) patients." (PMID 35864962, 2022).
diabetes (2 papers, 2021 to 2022). "This research might be useful in strategies for managing BC, and MEDAG could be a potential therapeutic target for BC in patients with diabetes." (PMID 35864962, 2022). "Therefore, MEDAG is a new potential therapeutic target for BC, especially in BC patients with diabetes." (PMID 35864962, 2022). "Given the critical role of MEDAG in both diabetes and tumor progression, MEDAG might be a promising therapeutic target for BC in diabetic patients." (PMID 35864962, 2022). "Therefore, MEDAG is a potential therapeutic target for BC in patients with diabetes." (PMID 35864962, 2022). "We found that MEDAG was highly expressed in BC patients with diabetes compared with nondiabetic BC patients." (PMID 35864962, 2022). "It is worth mentioning that no reports have clarified the role of MEDAG in diabetes mellitus." (PMID 33728329, 2021).
Obesity (2 papers, 2020 to 2022). Accumulation of substantial excess body fat. "Islet expression of MEDAG is different between diabetic and healthy individuals, and copy number variation in the MEDAG loci is associated with obesity." (PMID 33076817, 2020).
lymph node metastasis (1 paper, 2021). "The patients with lymph node metastasis also had a significantly higher percentage of MEDAG positivity than those without metastasis (P = 0.042)." (PMID 33462219, 2021).
meningioma (1 paper, 2017). A generally slow growing tumor attached to the dura mater. "AQP1, FRZB, PDGFRL, and PECAM1 were consistently underexpressed in meningioma samples; MEDAG, MYC, PAMR1, PDPN and PERP were consistently overexpressed in nearly every meningioma sample by both measurements." (PMID 29073243, 2017).
nodular goiter (1 paper, 2019). Goiter characterized by discrete tissue mass(es) that may or may not produce thyroid hormones. "MEDAG expression in nodular goiter and normal tissue was essentially negative as detected by IHC and WB analysis compared with PTMC at any TNM stage." (PMID 30967566, 2019).
ovarian carcinoma (1 paper, 2018). A malignant neoplasm originating from the surface ovarian epithelium. "Similar to CA11, MEDAG was in lower abundance in ovarian cancer ascites EVs." (PMID 29499737, 2018). "The predictors, LAMA4, CA11, MEDAG, NANOG, SPINT2, let-7b, miR23b, and miR29a were found to be sufficient to classify 87.5% and 100% of ovarian cancer (n = 8) and disease control (n = 10) groups, respectively." (PMID 29499737, 2018). "A previous study using microarray has also shown a lower MEDAG and LAMA4 expression in ovarian cancer compared to normal epithelial cells." (PMID 29499737, 2018). "In contrast to LAMA4, CA11, and MEDAG, the 2 mRNAs, SPINT2 and NANOG, were found to be increased in ovarian cancer ascites compared to peritoneal fluid EVs." (PMID 29499737, 2018). "Three mRNAs, CA11, LAMA4, MEDAG, were .01–.28-fold lower expressed and two mRNA, SPINT2 and NANOG, were 3.2–5.8-fold higher expressed in ovarian cancer ascites versus peritoneal fluid EVs." (PMID 29499737, 2018). "Based on previous studies relating to these mRNA, CA11 and MEDAG may be involved in maintaining malignant ascites microenvironment, while LAMA4, NANOG and SPINT2 activities could regulate ovarian cancer progression and metastasis." (PMID 29499737, 2018).
cancer (3 papers, 2018 to 2021). A tumor composed of atypical neoplastic, often pleomorphic cells that invade other tissues. "Then, the mechanistic experiments demonstrated that MEDAG regulated cancer progression and EMT through the AKT/AMPK/mTOR pathway." (PMID 33462219, 2021). "This study showed for the first time that MEDAG expression plays a role in cancer." (PMID 30967566, 2019). "Our result show that MEDAG localized to the cytoplasm in most classical PTMCs, but few lipid droplets were found in PTMC compared with para-cancer or adipose tissue, even when MEDAG was highly expressed in PTMC." (PMID 30967566, 2019). "The qPCR studies identified five mRNA (CA11, MEDAG, LAMA4, SPINT2, NANOG) and six miRNA (let-7b, miR23b, miR29a, miR30d, miR205, miR720) that were significantly differentially expressed between cancer ascites and peritoneal fluids." (PMID 29499737, 2018). "MEDAG staining was absent in the vast majority of para-cancer tissues (64/67, 95.5%)." (PMID 30967566, 2019).
tumor (3 papers, 2019 to 2022). "Therefore, our results showed the underlying mechanism by which HG promotes tumor progression via upregulation of MEDAG." (PMID 35864962, 2022). "Collectively, these results indicated that downregulation of MEDAG attenuated tumor growth and lung metastasis in vivo." (PMID 35864962, 2022). "The in vivo experiments indicated that the knockdown of MEDAG suppressed tumor growth and metastasis." (PMID 33462219, 2021). "The in vivo experiments also indicated that MEDAG deficiency suppressed tumor growth and metastasis in both diabetic and nondiabetic mice." (PMID 35864962, 2022). "The inhibition of MEDAG suppressed tumor growth and metastasis in vivo." (PMID 33462219, 2021). "MEDAG expression was detected in 65 out of 67 tumor samples (97%)." (PMID 30967566, 2019). "Finally, the mechanism of MEDAG in tumor progression and chemosensitivity was investigated." (PMID 33462219, 2021).
MEDAG also shares sentences with these, for which no sentence is quoted: abdominal aortic aneurysm (1 paper); colorectal cancer (1); glioma (1); myocardial infarction (1); serous ovarian adenocarcinoma (1).